RNU6-175P (RNA, U6 small nuclear 175, pseudogene)
Gene: Small nuclear RNA gene on chromosome 2 (132,406,752 to 132,406,858, reverse strand). Ensembl gene ENSG00000252705.
Homologues: Orthologues: chimpanzee U6 (100% identical), rabbit U6 (83% identical), rabbit U6 (82% identical), guinea pig U6 (81% identical), rabbit U6 (81% identical), rabbit U6 (79% identical), guinea pig U6 (79% identical). Paralogues in human: RNU6-1091P (89% identical), RNU6-727P (89% identical), RNU6-43P (88% identical), RNU6-1047P (87% identical), RNU6-1094P (87% identical), RNU6-1243P (87% identical), RNU6-1249P (87% identical), RNU6-562P (87% identical), RNU6-655P (87% identical), RNU6-820P (87% identical), RNU6-1141P (86% identical), RNU6-1152P (86% identical), and 1285 more.